ENSG00000238724
Synonyms: LOC124902825
Gene: Small nucleolar RNA gene on chromosome 11 (114,527,129 to 114,527,232, forward strand). Ensembl gene ENSG00000238724.
Gene Ontology:
Biological process: RNA processing
Cellular component: nucleolus
Homologues: Paralogues in human: SNORD13D (86% identical), SNORD13E (84% identical), SNORD13 (82% identical), SNORD13P3 (82% identical), SNORD13P1 (79% identical).